BCR (BCR activator of RhoGEF and GTPase)
Diseases named in the same sentence as BCR in open-access papers (continued):
Sharing a sentence is not in itself a finding about the gene and the disease.
leukemia (continued). "A parallel network, consisting of Wnt-JUP-MYC-BIRC5 axis, operates in BCR::ABL1-positive B-cell ALL, where JUP acts as a key driver required for leukemia maintenance." (PMID 41596324, 2026). "In B-ALL, we find that subpopulation dynamics are useful to predict BCR::ABL1 status and post-induction MRD (threshold frequency of 10−3 leukemia cells detected using specialized flow cytometry)." (PMID 41295979, 2026). "Our analysis suggests the existence of dedifferentiating transitions to a CD34+/CD38− stem cell–like immunophenotype in leukemia samples collected from patients with B-ALL, and the tendency for these transitions is especially strong in B-ALL with BCR::ABL1." (PMID 41295979, 2026). "We report that malignant transformation and transcriptional reprogramming by BCR::ABL1 is indeed defined by enhancer reprogramming and that enhancer signatures differentiate Ph+B-ALL from other leukemias." (PMID 41764406, 2026). "Here, we investigate how exosomes and BCR/ABL overexpression influence endothelial functions, aiming to identify key mediators of leukemia-induced microenvironmental remodeling as potential therapeutic targets." (PMID 41424711, 2025). "In contrast, BCR/ABL+, MLL+, and Ph-like ALL children had a high rate of persistent MRD positivity, reflecting the resistance of their leukemia cells to conventional chemotherapy." (PMID 41195225, 2025). "B cells develop properly by combining signals from IL7R and pre-BCR; however, when these signals are disrupted in B-ALL, they lead to the sustained growth of leukemia and actively drive leukemogenesis." (PMID 40709996, 2025). "The four most common leukemia genes in B-ALL children were ETV6/RUNX1, E2A/PBX1, MLL, and BCR/ABL in sequence." (PMID 41195225, 2025). "In a recent study using a murine Arf−/−Bcr-Abl1 mouse model, BCR::ABL1-specific CD4+ memory T cells played a protective role, with T cell depletion drastically increasing leukemia outgrowth after dasatinib or cytotoxic chemotherapy." (PMID 40503229, 2025). "XPO1 inhibition traps BCR–ABL in the nucleus, re-sensitizing leukemia cells to the BCR–ABL inhibitor imatinib and resulting in a substantial reduction in tumor cell proliferative potential with limited toxicity to normal myeloid precursors." (PMID 41440011, 2025). "In a BCR::ABL+ ALL mouse model, PD-L1 blockade led to clonal expansion of leukemia-specific CD4+T cells with a helper/cytotoxic phenotype, while reducing exhaustion marker expression." (PMID 40503229, 2025). "Expression of CD38 and CD49d is thought to be a poor prognostic factor as they help leukemia cells migrate and homing to secondary lymphoid organs and stimulate B-CLL cell proliferation in tandem with BCR signaling." (PMID 38560574, 2024). "We alsomade a vinylsulfonyl piperazine bearing derivative of the BCR-ABLand c-ABL kinase inhibitor dasatinib, ML 2–5, and demonstratedthe degradation of both the fusion oncogene and the parent kinasein K562 leukemia cancer cells." (PMID 39071058, 2024). "Indeed, the percentage of immature blast cells in the PB, leukemia cell infiltration in the spleen, the spleen weight and the percentage of Ki-67+ cells in the spleen were substantially increased after rmCXCL16 treatment in mice with secondary BCR-ABLtTA B-ALL cell transplantation." (PMID 38172124, 2024). "Consequently, testing for mutated BCR::ABL1 transcripts may not identify all resistant leukaemia cells." (PMID 38637690, 2024). "The BCR::ABL1 fusion gene produces the BCR::ABL1 tyrosine kinase, which leads to leukemia cell proliferation." (PMID 38034530, 2023). "In transgenic mice of p210 or p190 BCR::ABL1 under diverse promoters, leukemia progression has been widely confirmed." (PMID 35999358, 2023). "Herein, we identified a new signaling axis “BCR-ABL-TAL1-TSPAN32-PTEN-PI3K-AKT” and reveal its biological roles in BCR-ABL induced leukemias and TKI therapy." (PMID 36854750, 2023).
leukemia (continued). "Instead of inhibiting PARP using an inhibitor, we crossed Parp1 knockout mice with BCR/ABL1 Tg mice and examined leukemia development and death." (PMID 37165001, 2023). "The tyrosine kinase activity of the BCR::ABL1 protein is dysregulated, and primitive hematopoietic cellular homeostasis systems are changed by BCR::ABL1, which also increases leukemia cell proliferation." (PMID 37670241, 2023). "In broader terms, Drosophila has previously been successfully employed to model leukemia-like phenotypes of other human leukemic oncogenes, such as AML1-ETO, NUP98-HOXA9, and BCR-ABL." (PMID 37720104, 2023). "In CML, the components of UPS cooperate or antagonize the efficacy of TKI by directly or indirectly affecting the ubiquitination of BCR-ABL, interfering with CML-related signaling pathways, and negatively or positively affecting leukemia stem cells." (PMID 38947742, 2023). "Our knowledge of BCR::ABL1-positive leukaemias continues to evolve and with this, a personalised approach to leukaemia management continues to expand." (PMID 38550948, 2023). "We have used HAP1 cells as a model for CML, as HAP1 cells are derived from CML patient cells and have the BCR-ABL gene, which is common in leukaemia’s, turning the myeloid cell into a chronic myeloid cell, and IFN-I (IFNα2) as a treatment." (PMID 37958498, 2023). "miR-145 and miR-181 promote apoptosis of leukemia stem cells through regulation of ABCE1 and MCL-1 respectively, and miR-424 inhibits BCR-ABL activity." (PMID 37476380, 2023). "As previous reports have shown that BCR/ABL transduction confers these cells growth factor independence in vitro, and the transduced cells are able to generate a leukemia mouse model readily." (PMID 37864206, 2023). "In these murine models, the cooperation between BCR::ABL and the NUP98/HOXA9 gives rise to very aggressive leukemia in mice similar to acute leukemia." (PMID 37174060, 2023). "BCR::ABL1-independent PI3K/AKT pathway activation and imatinib resistance was also observed in primary leukaemia cells and in imatinib-treated CML patients." (PMID 35884363, 2022). "Compared to the wild-type BCR-FGFR1 and BCR-FGFR1m, the WBC levels in tnFGFR1 leukemic mice show a moderate increase, suggesting less mobilization of leukemia cells from the bone marrow into the peripheral circulation." (PMID 35906694, 2022). "This suggests that in targeted therapy for leukemia, SFK should be taken into account alongside BCR-ABL fusion protein." (PMID 36349200, 2022). "Firstly, a leukemia cell line, K56225, which has been established from a Ph1+ CML patient and carries the classical BCR-ABL fusion gene, was analyzed." (PMID 36042341, 2022). "These kinases are downstream targets of functional pre‐BCR (B‐cell receptor), a distinctive feature of human TCF3‐PBX1 leukemia, and two of its main targets after pre‐BCR stimulation are CrkL and PLCg2." (PMID 33890726, 2021). "It is demonstrated that Usp47 knockout significantly prolongs the survival of BCR-ABL and BCR-ABLT315I-induced CML mice by reducing leukemia stem/progenitor cells." (PMID 34454635, 2021). "One OEMR patient had evidence of a leukemia with TEL-AML fusion, and another patient was diagnosed with BCR-ABL fusion." (PMID 34830574, 2021). "The BCR-ABL fusion gene can be seen in CML patients, it is also found in other types of leukemia patients, such as acute myeloid leukemia (AML) patients, B-cell acute lymphoblastic leukemia (B-ALL) patients, and mixed phenotype acute leukemia (MPAL) patients." (PMID 33748144, 2021). "Analyzing mRNA expression of BCR/ABL and WT1 of ocular fluid in patients with hypopyon is beneficial in diagnosing topical relapses in leukemia." (PMID 31977890, 2020). "The best analogy is BCR-ABL international scale detection for deep molecular and ultra-deep molecular response in Philadelphia positive leukemias." (PMID 32164715, 2020).
leukemia (continued). "Pharmacological targeting of BCR/ABL1 by imatinib and its successors have converted CML from a deadly disease to leukemia with very good prognosis." (PMID 33322186, 2020). "The pronounced anti-proliferative effects of Cdk8 deletion in murine leukemia cells were unexpected and indicate the unique role of CDK8 downstream of BCR-ABL1p185+ in murine B-ALL." (PMID 31628323, 2019). "The BCR-ABL translocation is thus referred to as the Philadelphia chromosome, and resulting leukemias are referred to as Ph+ leukemias." (PMID 31105873, 2019). "At present, the use of ABL kinase inhibitors (e.g. imatinib) for the treatment of CML can inhibit the activity of BCR-ABL kinase effectively, inhibit the malignant proliferation of leukemia cells, and extend the survival time of patients significantly." (PMID 31074387, 2019). "The samples were labeled by prognostic leukemia subtype [‘TEL-AML1’, ‘BCR-ABL’, ‘MLL’, ‘Hyperdiploid (>50)’, ‘E2A-PBX1’, ‘T-ALL’ and ‘Other’]." (PMID 30010791, 2019). "Chronic myelogenous leukemia (CML) is an important hematological tumor that is characterized by the BCR-ABL chimera gene and occurs in 15 to 20% of adults with leukemia." (PMID 30845905, 2019). "K562G cell was derived from K562, a human cell line of CML positive for BCR-ABL and widely used for leukemia research." (PMID 29707241, 2018). "In several types of leukemia it has been shown that the pre-leukemic stem cell (pre-LSC) possesses multilineage potential; this is the case in CML, where pre-leukemic BCR-ABLp210+ stem cells can give rise to all different blood cell types." (PMID 29772764, 2018). "The combination of donor and ZFNs demonstrated here is able to truncate BCR-ABL oncoprotein efficiently in CML cells and CML CD34+ cells and show the anti-leukemia ability in vitro and in vivo." (PMID 29554925, 2018). "Collectively, these observations are consistent with reduced disease latency and more aggressive leukemia in Gadd45a−/−/BCR-ABL mice, pointing to a potent and novel tumor suppressor role for Gadd45a in BCR/ABL driven leukemogenesis." (PMID 28086219, 2017). "Similar to leukemias induced by Hoxa9+BCR/ABL, these leukemias also are characterized by expansion and infiltration of myeloid blasts into the bone marrow, spleen, and liver." (PMID 29228732, 2017). "To elucidate the exact anti-leukemia mechanism of SPOA, we tested the effect of SPOA on the binding of BCR-ABL with GRB2, and the signal activation by BCR-ABL." (PMID 27926512, 2017). "Because the CFTR inhibitor showed a strong anti-leukemia effect, we sought to determine the effect of down-regulating CFTR expression on BCR-ABL and classic Wnt/β-catenin signaling." (PMID 28445932, 2017). "Resembling mice with Hoxa9+BCR/ABL and Hoxa10+BCR/ABL leukemias, the bone marrow, spleen and liver of the moribund mice were infiltrated by immature leukemia blasts, representing 31 ± 5.7% (Mean ± SD) of all nucleated cells in the bone marrow." (PMID 29228732, 2017). "Using label-free Raman spectromicroscopy, we evaluated a number of leukemia cell lines and discovered an aberrant accumulation of cholesteryl ester (CE) in CML, which was found to be a result of BCR-ABL kinase activity." (PMID 28719608, 2017). "Different from GMP-derived leukemias induced by Setbp1 and BCR/ABL, Hoxa9+BCR/ABL and Hoxa10+BCR/ABL leukemias are mostly monoclonal in origin, suggesting that additional mutation(s) is likely required for the transformation in both cases." (PMID 29228732, 2017). "In this study, we designed a dephosphorylation and degradation system targeting BCR-ABL Y177 termed SPOA, and tested its anti-leukemia activity in vitro and in vivo." (PMID 27926512, 2017). "Consistent with their co-transduction by BCR/ABL and Hoxa10 viruses, these leukemia cells expressed high levels of BCR/ABL and Hoxa10." (PMID 29228732, 2017).
leukemia (continued). "In this review, we will consider the BCR-ABL/NF-κB crosstalk with relation to the development and maintenance of leukemia and we will debate the potential therapeutic strategies to block NF-κB signaling in Ph+ malignancies." (PMID 27563822, 2016). "While it was originally developed for targeting the BCR-ABL gene fusion, it exhibits nanomolar range activity against PDGFRA in leukemia." (PMID 27582545, 2016). "Following confirmation of efficient uptake of Au-NPs into leukemia cells, we tested dasatinib-DNA Au-NPs with K562 leukemia cells that express BIRC5 mRNA, harbor a dasatinib-sensitive BCR/ABL translocation, and exhibit high SRC kinase activity." (PMID 27203672, 2016). "SHP2 and Gab2 have been demonstrated to be required for BCR/ABL-induced myeloid transformation and leukemia cell proliferation, suggesting that the Gab2-SHP2 axis is an important signaling event in leukemia." (PMID 26095858, 2015). "In summary, these data indicate that the co-expression of p96ABL/BCR and p185BCR/ABL shifts the leukemia from a myeloproliferative disease upon p185BCR/ABL alone to ALL." (PMID 25919613, 2015). "It results in BCR–ABL fusion protein, with a continuously activated tyrosine kinase activity, thus promoting the unrestrained cell division of leukemia cells." (PMID 24711808, 2014). "We investigated the efficacy of imatinib and TG101348 using the break point cluster region-c-Abelson (BCR-ABL)-positive cell line and primary CML samples wherein leukemia cells were protected by a feeder cell line (HS-5)." (PMID 24775308, 2014). "This promoter was chosen as attempts to use the BCR promoter to drive expression of BCR-ABL, as occurs in human leukemia, led to embryonic lethality of mice." (PMID 24847444, 2014). "It is anticipated that a larger sample size of each leukemia subtype would be required to accurately address the relationship between MKRN2 and RAF1, as well as between specific translocations such as BCR-ABL." (PMID 24675897, 2014). "In Philadelphia chromosome (Ph) positive leukemias, activation of PI3K by dysregulated BCR-ABL tyrosine kinase (TK) contributes to the pathogenesis and development of resistance to ABL-TK inhibitors (TKI)." (PMID 24244612, 2013). "The authors could show that the peptide interacted with BCR/ABL endogenously expressed in leukemic cell lines and, as a consequence, led to a decrease in cell growth and induction of apoptotic death specifically in cells expressing the leukemia-associated fusion protein." (PMID 23865046, 2013). "MCL-1 has been identified as a BCR/ABL-dependent survival factor in CML and acts as an anti-apoptotic factor in various neoplastic cells, including several leukemia-derived cell lines." (PMID 23596478, 2013). "In a murine transplant model, vaccinated mice demonstrated decreased leukemia cell infiltration and reduced BCR-ABL transcript and protein expression in bone marrow cells with a BCR-ABL-GPI-mIL12 vaccine." (PMID 23394714, 2013). "It has been reported that PML (promyelocytic leukemia protein) plays a role in normal HSCs and BCR-ABL transduced quiescent LSCs, facilitating leukemia initiation and maintenance." (PMID 21297225, 2010). "For example in the pair (IGFI, IGFII) the genes are both members of the family of insulin-like growth factors, and in the pair (BCR, ABL1) the fusion of the BCR and ABL1 genes has been found to be a "recurrent aberration in B cell precursor leukemia cells"." (PMID 15847682, 2005). "Overall, the BCR::FGFR1 translocation is extremely rare, which prompted us to conduct a literature review upon diagnosis, revealing descriptions of rapidly progressive and challenging-to-treat leukemia." (PMID 41180818, 2025).
leukemia (continued). "Although BCR::ABL1-positive B-ALL did not correlate with any specific marker (p = 0.34), all cases in this series exhibited at least one leukemia-associated immunophenotype (LAIP) suitable for MRD monitoring via flow cytometry." (PMID 40076750, 2025). "SIAIS178 demonstrated selective antiproliferative activity against BCR-ABL CML cells, but not in BCR-ABL negative leukaemia lines such as U937, HL-60, or HEK293 cells, highlighting its selectivity." (PMID 40793752, 2025). "In conclusion, this case underscores the clinical imperative of utilizing molecular diagnostics, particularly whole-transcriptome sequencing, in instances where conventional BCR::ABL1 assays yield negative results despite cytogenetic evidence of Ph+ leukemia." (PMID 41211450, 2025). "Notably, all of these genetic abnormalities can present as distinct single lineage leukemias (e.g., B-ALL with BCR::ABL1 fusion) but are classified as ALAL/MPAL based on meeting MPAL/ALAL immunophenotypic criteria." (PMID 40075717, 2025). "Here, we report the targeted siRNA-based lipid nanoparticles in Ph+ leukemic cell lines for gene therapy of Ph+ leukemia, which specifically targets a recently identified NEDD8 E3 ligase RAPSYN in Ph+ leukemic cells to disrupt the neddylation of oncogenic BCR-ABL." (PMID 38741123, 2024). "The adverse impact of CD9 was confined to specific cytogenetics, notably BCR::ABL1+ rather than KMT2A-rearranged leukemia." (PMID 38001171, 2024). "New evidence emphasizes the crucial role of BCR::ABL1-independent pathways, particularly the importance of leukemia stem cells that persist and sustain the disease even in the absence of BCR::ABL1 kinase activation." (PMID 38607055, 2024). "In this study, we established a virus-mediated Cas9/dual-sgRNA-mediated disruption of the BCR-ABL fusion gene that could significantly reduce Ph expression and abolish leukemia cell survival and tumorigenic abilitiesin vitro andex vivo." (PMID 38414349, 2024). "Thus, mimicking the initiation process of translocation, we induced CRISPR/Cas9-mediated DSBs simultaneously at the breakpoints of the BCR and ABL1 genes in a granulocyte-macrophage colony-stimulating factor (GM-CSF) dependent human leukemia cell line." (PMID 35999358, 2023). "All TKIs block the BCR-ABL aberrant molecule, shutting down the leukemia phenotype." (PMID 36751250, 2023). "Finally, BCR::ABL+, BMI1+, and BCR::ABL+/BMI1+ CD34+ cells were transplanted into NOD/SCID mice to test for leukemia induction in vivo." (PMID 38201282, 2023). "Thus, we induced DSBs at specific breakpoints of BCR and ABL1 genes, using the CRISPR/Cas9 system in a human factor-dependent leukemia cell line." (PMID 35999358, 2023). "The authors showed that three months after bone marrow transplantation, an increase in the BCR/ABL transcript was observed in this group of 15 patients, which correlated with a high 3-year cumulative incidence of relapse and worse leukemia-free survival and overall survival." (PMID 37675394, 2023). "Although leukemia progression was not achieved by simple transplantation of human CD34 + cord blood cells retrovirally transduced with p210 BCR::ABL1 cDNA into NOD-SCID mice, simultaneous transduction of BMI1 cDNA induced ALL progression." (PMID 35999358, 2023). "More precisely, targeting a single mutation (as tyrosine kinase inhibitors for BCR::ABL1 fusion gene, FLT3 or IDH1/2 mutations) is not the “magic bullet” since leukemia heterogeneity will allow tumor escape via clonal drift under chemotherapy pressure." (PMID 37444390, 2023). "BCR/ABL is a fusion kinase only present in certain leukemia cell lines, not HEK293 cells, leaving six targets of interest." (PMID 36338985, 2022). "In cells that are not vulnerable to negative selection, BCR stimulus can also contribute tonic survival signals, and therefore leukemias often demonstrate alterations in B-cell developmental progression that favor survival." (PMID 35354797, 2022).